OCLN (occludin)
Diseases named in the same sentence as OCLN in open-access papers (continued):
Sharing a sentence is not in itself a finding about the gene and the disease.
infection (249 papers, 2009 to 2026). The state of being infected such as from the introduction of a foreign agent such as serum, vaccine, antigenic substance or organism. "This invasive phenotype, which we term C. jejuni supercoiling induced (SI), led to marked disruption of tight junctions (TJs) and adherens junctions, as evidenced by the loss of occludin and β-catenin signal during infection." (PMID 40471665, 2025). "The MZ group exhibited a significant downregulation in tight junction-associated protein expression, such as claudin-1, occludin, and ZO-1, which suggests that the infection weakens the intestinal epithelial barrier’s structural integrity." (PMID 41060041, 2025). "After 6-h infection, C. jejuni (SI) had caused localized disruption of TJs and total disruption of occludin intensity by 24 hpi." (PMID 40471665, 2025). "Infection with Aa and/or Sg induced changes in the transcriptional profile of genes encoding TJ proteins claudin 1, claudin 2, and occludin and the anchoring protein zonulin in the intestinal barrier." (PMID 39125663, 2024). "As expected from the TEER values, infection with the Delta variant showed large syncytia formation as visualized by N-positive cells and disruption of and reduction in occludin and β-catenin staining." (PMID 36827451, 2023). "During infection, this secreted protease cleaves the tumour suppressor E-cadherin in the adherens cell-to-cell junctions as well as claudin-8 and occludin in the tight junctions, which causes severe damage in the infected gastric epithelium." (PMID 37183214, 2023). "Treatment of keratinocytes with this peptide resulted in decreased TEER, altered expression and/or localization of tight junction-related proteins (claudin-1 and occludin), and increased susceptibility to infection with VV." (PMID 37737609, 2023). "The precise mechanism of occludin redistribution caused by SS2 infection requires further exploration." (PMID 35921364, 2022). "In this study, we observed loss of TEER and reduced junction coverage of occludin in iBECs co-cultured with LMCs after 24 h of infection." (PMID 36289516, 2022). "OCLN overexpression in target cells increased PEDV infection, and the entry of virus is closely associated with internalization of OCLN." (PMID 36297257, 2022). "Orangutan-adapted infection causes increased permeability of the TJs by downregulating OCLN and ZO-1 in the lungs." (PMID 36297257, 2022). "In primary polarized cells of the endocervix, infection with gonococci caused also the disruption of tight junctions and the redistribution of Occludin and ZO-1." (PMID 33014885, 2020). "In characterizing the role of occludin in PSaV entry, the ectopic expression of occludin in CHO cells rendered them susceptible to infection." (PMID 30463963, 2019). "The results of the present study indicate that cell infection with P. gingivalis promoted the expression of the TJ genes encoding occludin, claudin-1 and claudin-4, which enhances barrier function and decreases cell-cell permeability." (PMID 29319048, 2018). "Occludin, Claudin -1 and β-catenin are tight junction protein which gets manipulated during pathogenic infection and blood-brain barrier breaching." (PMID 30001342, 2018). "We recently confirmed a role for TJ-associated occludin in the T. gondii paracellular route of infection using m-ICc12, an in vitro murine SI epithelial cell line." (PMID 28452683, 2017). "The loss of occludin staining at days 6–10 implied severe damage in the inter-endothelial junctions, as described in other infection models." (PMID 28742087, 2017). "Analysis of lysates at 22 h post-infection revealed that S. Typhi induced both a loss of occludin and hyperphosphorylated occludin from the insoluble fraction and a shift of the signal to the soluble fraction in all Salmonella strain-treated samples." (PMID 23408152, 2013). "More recently, OCLN splice variants were examined and suggested to possibly contribute to tissue tropism and outcomes of infection." (PMID 21994703, 2010).
infection (continued). "Direct infection of HaCaT keratinocytes with wild-type C. albicans caused a significant decrease in the mRNA expressions of all three TJ genes, whereas indirect exposure to the wild-type caused a significant decrease in OCLN and JAM1." (PMID 41590450, 2026). "Interestingly, lower Occludin levels have been associated with facilitating Tg infection as well as protecting epithelial cells from infection." (PMID 38950025, 2024). "TJ are responsible for the integrity and function of the epithelial barrier, and once damaged, the risk of infection with exogenous pathogens will greatly increase; ZO-1 and occludin are known to play a primary role in the maintenance of the epithelial barrier." (PMID 32106883, 2020). "Infection by S. Typhimurium causes a fast and progressive increase in the permeability of polarized epithelial monolayers and induces alterations in the localization of the TJ-associated proteins ZO-1 and occludin." (PMID 29932149, 2018). "In contrast, infection of Caco-2 cell monolayers with ST-7 (C and G) led to focal disruptions and punctate concentration along pericellular junctions, while there was almost a complete loss of occludin in H-treated cells." (PMID 24851944, 2014). "Human OCLN was also able to render mouse cells susceptible to HCVpp infection, along with expression of human CD81, suggesting that OCLN may be a species-restricting determinant of HCV infection." (PMID 21994703, 2010). "Correspondingly, we found that the infection impaired the colonic barrier integrity, evidenced by the fewer ZO-1+ cells and the downregulated mRNA expression of tight function proteins associated genes (ZO-1 and occludin) in the colon, and the elevated levels of LPS and FITC-dextran." (PMID 39182245, 2024). "Direct infection with either the wild-type C. albicans or the Cacfl11Δ mutant significantly decreased the OCLN mRNA expression; however, the effect was less prominent upon infection with Cacfl11Δ." (PMID 41590450, 2026). "TCID50 assays revealed that viral titers in the supernatant of cells with OCLN or ZO-1 knockdown were markedly elevated compared to the control infection group at 12 and 24 hpi." (PMID 40880512, 2025). "The expression of ZO-1 and Occludin remained largely unchanged in V2 and KO cells, but decreased significantly upon infection with WT or ΔespF strains." (PMID 41522448, 2025). "Infection nonetheless led to the upregulation of adhesion molecules and tight-junction genes, with occludin, a specific marker of tight junctions, showing stronger expression after infection with African strains." (PMID 41305388, 2025). "Occludin also maintains hepatocyte polarity and enhances infection efficiency by promoting the co-localization of the CD81/Occludin receptor complex." (PMID 40142587, 2025). "Untreated C. jejuni had a minimal effect at 6 hpi but was capable of localized disruption of occludin signal after 24-h infection, while still maintaining low adherent numbers." (PMID 40471665, 2025). "In this study, we observed the elevated levels of both claudin-4 and occludin during infection with CagA+H. pylori strains." (PMID 41341493, 2025). "To understand the correlation between the RhoA/ROCK1/MLC2/Occludin pathway and MVC infection, we analyzed the protein expression levels of Occludin in WRD cells infected with MVC and evaluated the effects of RhoA and ROCK1 inhibitors on its expression." (PMID 40142587, 2025). "Consistent with this, we found that the NDV NP protein and the TJ protein OCLN accumulate within these cage-like structures during infection." (PMID 40880512, 2025). "In weaned piglets from both PEDV groups, there was a slight increase in OCLN transcriptional expression, while the ZO-1 gene was significantly upregulated post-infection." (PMID 40589734, 2025). "Infection of HOKs with P. gingivalis, the key periodontal pathogen, significantly downregulated OCLN, CLDN1, and CDH1." (PMID 41358003, 2025).
infection (continued). "In contrast, OCLN and ZO-1 expression, though variable across cell types, generally shows a downward trend after infection." (PMID 40880512, 2025). "Co-staining intensities for both ZO-1 and occludin becomes markedly less evident following HRV-1b infection (white arrow)." (PMID 40641604, 2025). "Post-infection, a slight decrease in the expression of certain TJ genes, notably claudins (Cldns), occludin (Ocln), and junctional proteins (Tjps), was observed." (PMID 40786607, 2025). "M22 administration enhanced antioxidant capacity, alleviated infection-induced inflammation, and preserved intestinal barrier integrity by restoring villus morphology and upregulating tight junction proteins (ZO-1 and occludin)." (PMID 41156810, 2025). "Specifically, ZO-1 expression decreased significantly early in infection (at 1 dpi), whereas occludin and claudin-3 levels significantly declined from 3 dpi, reaching their nadir at 7 dpi." (PMID 39799330, 2025). "The results showed that GPS infection significantly decreased the expression of ZO-1 (p < 0.05), Occludin (p < 0.01), and Claudin-5 (p < 0.05) in the mouse cerebrum." (PMID 38927100, 2024). "As expected, inflammation score (as measured by cell infiltrates and lack of epithelium integrity) and Il-22 levels increased with Tg infection while Zo1 and Occludin levels decreased." (PMID 38950025, 2024). "MUC17 silencing in Caco-2 and HT29-19A cells resulted in a profound reduction of occludin and ZO-1 levels and an increase in paracellular permeability after infection with enteroinvasive E. coli compared to WT cells." (PMID 38345099, 2024). "In cells infected with wild-type SC1401, the levels of claudin-1 and occludin increased through 12 h and 36 h of infection, respectively, before decreasing to time 0 levels or lower." (PMID 38674155, 2024). "Analysis of murine colons following infection showed that mice infected with C. difficile had significantly downregulated colon tight junction proteins (TJPs; ZO-1, OCLN, and CLDN4)." (PMID 38193707, 2024). "To further assess the effects of N. meningitidis on the localization of ZO-1 and occludin, we analyzed Calu-3 cell layers after 24 h of infection with MenB:cc32 and MenW:cc22 strains using confocal microscopy." (PMID 38756230, 2024). "Epithelial barrier dysfunction is characterised by decreased levels of Zo1 and Occludin, which has been observed during Tg infection both at the gene expression and protein levels." (PMID 38950025, 2024). "The relative mRNA expression of ZO-1, Claudin-1, and Occludin in the ileum and colon was significantly decreased after S. Typhimurium infection, especially 72 hours post-infection." (PMID 39435479, 2024). "RV-A1-infection increased occludin protein expression in placebo-treated cells at 24 h post-infection, which returned to basal level after 72 h." (PMID 39538325, 2024). "The Western blot results showed that the levels of occludin and collagen IV in Yb2- and cYb2ΔsspA-infected cells decreased gradually with increasing infection time compared with those in control and Yb2ΔsspA-infected cells." (PMID 38594770, 2024). "We compared the regulation of Egr-1 on the TJ proteins, including ZO-1, Occludin, and Claudin-5 in both Egr-1−/− and WT hBMEC in response to the infection." (PMID 38233877, 2024). "On the day 1 of infection, the mRNA transcript levels of tight junction proteins (Claudin-1 and Occludin) and mucin (MUC-2) were significantly reduced in the jejunum and ileum of chicks in the SP group compared to the NC group." (PMID 38863452, 2024). "In cells infected with ΔEspP2::Kan, levels of occludin and claudin-1 decreased significantly throughout the 48 h infection." (PMID 38674155, 2024). "The results demonstrated down-regulation in the transcription and expression of the MUC–2 protein and the tight-junction proteins of occludin and ZO–1 upon PAstV–4 infection." (PMID 38891045, 2024).
infection (continued). "Infection at day 4 led to single infected cells, which correlated with a strong enrichment of occludin at lateral membranes in the most apical granular layer, as shown by whole-mount stainings." (PMID 37289055, 2023). "We next investigated the endothelial cell gene expression of tight junction proteins (ZO-1, JAM-A, Occludin and Claudin-5) and adherens junction protein (VE-Cadherin) in response to 2, 4 or 6 days of infection with SARS-CoV-2." (PMID 37537664, 2023). "The WB results showed the expression level of those proteins, including VE-cadherin, claudin-5, and occludin in infected hCMEC/D3 cells were significantly lower at 48 h post-infection with viral dose dependence compared to the mock group." (PMID 37773164, 2023). "CRISPR/Cas9-mediated knockout of the OCLN gene suppresses infection of the human liver cell line Huh7.5.1-8 with various HCV genotypes." (PMID 38203503, 2023). "And B. subtilis BS1-ql and complex probiotics enhanced intestinal tight junctions and reduced infection by upregulating the mRNA expression level of Occludin gene." (PMID 37138630, 2023). "Further molecular analyses showed a significant decrease in occludin and VE-cadherin protein expression levels at 24 h post-infection compared to controls." (PMID 37245027, 2023). "There was a significant reduction (average 80.4% and 78.3%) of cells positive for SARS-CoV-2 after infection at MOIs of 0.01 and 0.1 in OCLN knockdown Vero-E6 cells compared to control siRNA–treated cells." (PMID 37068248, 2023). "The opposite occurs during infection of Vero-E6 cells by PEDV in which OCLN is the primary entry factor, but its expression becomes up-regulated rather than diminished." (PMID 37068248, 2023). "More continuous occludin stainings were observed at day 4 indicating mature TJs, which correlated with infection of only some cells." (PMID 37289055, 2023). "Claudin-5 mRNA levels decreased at earlier time points (24-h) after infection while occludin mRNA levels remained unchanged." (PMID 37245027, 2023). "In influenza/H1N1 and HIV infections, a decrease in occludin levels has been shown to increase infection." (PMID 37840143, 2023). "Protein expression levels of β-catenin and occludin were significantly decreased post-infection by APP in contrast to those of uninfected control cells." (PMID 37511601, 2023). "Infection of polarized CFBEs with P. aeruginosa (MOI = 20) for 6 h dramatically decreased organization of occludin-stained tight junctions compared to cell culture medium alone." (PMID 36472421, 2023). "Vitamin B12 increased Zo-1, Occludin, and Claudin15 expression in the mRNA level (P < 0.05) while the infection decreased the expression of these genes." (PMID 37322528, 2023). "Claudin-5 mRNA levels decreased at earlier time points (24-hours) after infection while occludin mRNA levels remained unchanged." (PMID 36778380, 2023). "After three days of infection, infected cells showed clear aberrations in the distribution of the TJ protein Occludin." (PMID 37139492, 2023). "Experiments are currently underway in our lab investigating the importance of the L/S171 mutation in HtrA-mediated cleavage of cell junction proteins occludin, claudin-8 and E-cadherin during infection." (PMID 37183214, 2023). "Upon infection with salmonella, OCLN becomes dephosporylated and subsequently removed from epithelial tight junctions." (PMID 35371085, 2022). "Consistent with in vitro results, PEDV intranasal infection resulted in considerable degradation of ZO-1, OCLN, and CLDN-1 in nasal microvessels." (PMID 35435723, 2022). "In similar, ursodiol intervention markedly suppressed the increases in IκBα phosphorylation after E. coli 1587 infection, and occludin expression was upregulated." (PMID 35643532, 2022). "During T. spiralis infection, the expression of the gut epithelial TJ proteins occludin and claudin-3 was found to be downregulated beginning at 2 days post-infection, whereas claudin-2 was overexpressed." (PMID 35255974, 2022).
infection (continued). "PCV2 downregulates ZO-1 and OCLN in the lung and increases the permeability of the tracheal epithelial barrier to facilitate its infection." (PMID 36297257, 2022). "Our results showed that the expression of Occludin declined significantly in the E. coli E44 infection group compared with the uninfected group (p < 0.01)." (PMID 36289622, 2022). "In the control cells, ZO-1 and occludin were evenly distributed at the cell boundary; in the WT infection group, ZO-1 and occludin delocalized from the apical junctions, and an increase in cytosolic occludin was observed." (PMID 35921364, 2022). "As many studies reported, the infection of C. perfringens can reduce the mRNA expressions of ZO-1 and occludin in broilers through the activation of NF-κB signaling pathway." (PMID 35436978, 2022). "In the Δatl infection group, similar to that observed in the control cells, there was a slight disturbance of ZO-1 and occludin." (PMID 35921364, 2022). "As before, the raised level of IκBα phosphorylation post ESBL-EAEC infection was markedly blocked by GA intervention, with marked upregulation of occludin protein expression level." (PMID 35399688, 2022). "In Huh7.5 cells, TACSTD2 interacts with CLDN1 and OCLN and effectively activates PKC-mediated phosphorylation of CLDN1 and OCLN, which is required for their proper cellular localization, and in order to facilitate the infection of HCV." (PMID 36297257, 2022). "PA-induced nuclear accumulation of NF-κB, MMP-8 activation, and subsequent occludin degradation were blocked by caAMPKα infection." (PMID 35915511, 2022). "al. showed that both occludin and claudin-5 levels were significantly downregulated during infection." (PMID 35328419, 2022). "We found that serum DAO activity and D-lactate concentration associated with intestinal barrier integrity were distinctly increased, which is in accordance with the down-regulated intestinal protein levels of occludin and ZO-1 during NE infection." (PMID 35387091, 2022). "As expected, immunofluorescence showed that occludin was displaced from the plasma membrane after infection with 178119, but it remained at the plasma membrane after infection with YS-3, YS-13, and 148233." (PMID 35358181, 2022). "Exposure of pericytes to HIV-1 significantly decreased occludin levels 48 h after infection, followed by significant increases in caveolin-1 and alix expression which steadily climbed to both 48 and 72 h after infection." (PMID 36476484, 2022). "Compared to mock-infected groups, Claudin 1 (CLDN1) and CLDN4 were significantly upregulated, while CLDN8 and Occludin (OCLN) were downregulated in the HP-PRRSV infection group." (PMID 35336858, 2022). "Within 48 h of pericyte infection by HIV-1, there is a significant increase in viral replication, which is associated with NFKB acetylation and a decrease in occludin expression." (PMID 36476484, 2022). "The G. parasuis serotype 5 SQ strain (HPS5-SQ) infection decreased the integrity of piglets’ lung Occludin and Claudin-1." (PMID 36228044, 2022). "The mRNA levels of claudin-1, claudin-3, claudin-7, claudin-11, occludin and ZO-1 were all downregulated in the case of infection with A. hydrophila (P < 0.05)." (PMID 34220849, 2021). "APEC XM and APEC ΔclbH/pclbH infection resulted in a significant decrease in ZO-1, occludin, and claudin-5 protein expression compared to that in the control group (p < 0.01)." (PMID 34529552, 2021). "Western blot analysis shows that the expression of the TJ ZO-1 and occludin decreased during HPS4-YC infection." (PMID 34674760, 2021). "After infection with C. jejuni the TJ proteins, occludin and claudin-5 were redistributed off the TJ domain of the epithelial cells." (PMID 33935732, 2021). "Under pathological conditions, such as inflammation, ischemia, and infection, the downregulation of occludin in the endothelial cells in brain microvessels is closely related to the increased BBB permeability." (PMID 34266350, 2021).